KRAS (KRas proto-oncogene, GTPase)
Diseases named in the same sentence as KRAS in open-access papers (continued):
Sharing a sentence is not in itself a finding about the gene and the disease.
tumor (continued). "Besides the immune-related nature of KRAS driven tumors, the smoking habit of patients with KRAS mutations has been associated with higher tumor mutational burden (TMB), which might predict better responses to ICI." (PMID 35096591, 2021). "Moreover, exogenous IL-33 mimicked the effects observed in case of injury and cooperated with KRAS mutation to activate the neoplasia-specific and BRD4-dependent gene expression program, associated with an accelerated appearance of pancreatic intraepithelial neoplasia." (PMID 34023857, 2021). "It would have been of interest to see how the expression of STK11 differed in the context of the presence of other comutations like KEAP1 or KRAS and to analyze the tumor microenvironment, as the composition of different immune cells might be different among different KRAS mutations." (PMID 33572782, 2021). "In addition, we found a close relationship between tumour grade and KRAS mutation." (PMID 34557315, 2021). "KRAS mutations have been identified in early stage endometrial hyperplasia specimens and due to their biological function to support tumor proliferation, by assessing the presence of this mutation may offer an opportunity to predict tumor invasiveness." (PMID 33801965, 2021). "Also some novel biomarkers were investigated to predict the survival outcome of PSC, such as CD8+ tumor-infiltrating lymphocytes, the epithelial−mesenchymal transition transcription factors (Twist1), the change of neutrophil-to-lymphocyte ratio, KRAS mutations and c-MET overexpression." (PMID 34136380, 2021). "Several studies suggested that CIMP-positive tumors can lead to a poor overall survival prognosis, and show a close correlation with clinicopathological and molecular characteristics, including tumor location, gender, and whether there are KRAS and BRAF mutations." (PMID 34321009, 2021). "Though, it is possible the previous panel-based sequencing only included the more common codon 12 and codon 13 to establish mutation status and therefore may have incorrectly classified the patient’s tumor as KRAS WT instead of as a KRAS (A146T) mutation positive." (PMID 34504655, 2021). "Thus, there is an important selection bias, as the cases that we hypothesize will lack KRAS somatic mutations in the primary tumor were excluded." (PMID 33807330, 2021). "Moreover, receiver operating characteristic (ROC) curves for maximum standard uptake value (SUVmax) of the primary tumor were generated along with analysis of the target tissue to nontarget tissue ratio (T/NT) for predicting the efficacy of KRAS/NRAS/BRAF mutations in CRC." (PMID 34239564, 2021). "However, if KRAS mutation status of primary tumor may be representative of the corresponding CRLM mutational pattern, is debatable." (PMID 33946899, 2021). "Both PCR and direct sequencing could detect the KRAS G12C mutation in three tumor tissues." (PMID 33467412, 2021). "In the “water-burst” method, we could detect even a small number of cells with a homozygous KRAS mutation at codon 12, in as low as 20 cells (= 40 copies) in 4,000 normal cells with wild-type KRAS, showing that it was feasible to detect dPCR-based direct driver mutations in crude tumor tissues." (PMID 32704002, 2020). "Yet, endogenous TRAIL–TRAIL-receptor signaling can be therapeutically targeted and, excitingly, this may not only counteract oncogenic KRAS-driven cancer cell migration, invasion, and metastasis, but also the immunosuppressive reprogramming of the tumor microenvironment it causes." (PMID 32194994, 2020). "In the current study, 44 patients were tested for tumor gene mutations, and multiple statistical analysis methods (lasso regression + logistic regression + machine learning random forest algorithm) were used to find that patients with KRAS mutations benefited from PD‐1 blockade." (PMID 32342665, 2020).
tumor (continued). "Due to the impact of KRAS being largely cell type-dependent, the analysis of oncogenic mutations in non-transformed acinar cells is critical to characterize the precise mechanism of tumor initiation and possibly identify targetable processes to prevent cancer onset." (PMID 32932616, 2020). "Based on a previously published work, the Authors speculated that the concomitant loss of STK11 together with mutations in an oncogenic pathway (KRAS/RAF) promotes IL-6 secretion by tumor cells, which, in turn, can determine the recruitment of neutrophils in the tumor microenvironment." (PMID 33168050, 2020). "Interestingly, this patient's tumor next-generation sequencing analysis showed a pathogenic mutation in KRAS G12R (seen in ∼20% of PC), which may have an impaired ability to activate PI3K-mTOR signaling." (PMID 32642630, 2020). "Notably, activation of the RAS signaling was one of typical characteristics under hypoxia and this association may through EST1 to activate the RAS pathway in a non-KRAS mutation-dependent manner to promote tumor proliferation and metastasis." (PMID 33330037, 2020). "Finally, we found that YB-1 has a crucial role in tumor growth of KRAS-mutated TNBC cells in vivo." (PMID 33003386, 2020). "Moreover, we describe the first UrAC cell line (MISB18) with a known tumor genomic profile, which together with future analyses of additional ex vivo UrAC samples can be used as a model to establish the role for pathogenic KRAS mutations on UrAC pathophysiology and drug sensitivity." (PMID 32576176, 2020). "Previous controversial reports have evaluated intertumoral heterogeneity, showing both discordance and concordance in the KRAS mutation status between the primary tumor and the matched metastases, thus intertumoral heterogeneity might implicate a clinical problem in CRC." (PMID 33002027, 2020). "However, it cannot be excluded that additional mutations in the tumor, like KRAS or BRAF, might influence FAM83A and/or B expression." (PMID 31083571, 2019). "The hypothesis that mutant KRAS peptide itself is among the involved antigenic targets is especially attractive since, in contrast to other neoantigens, the driver mutation is a sensitive component of tumor survival." (PMID 31665076, 2019). "In addition, the expression of miR-193a-3p was found to be associated with KRAS mRNA, which indicated that miR-193a-3p could act as a tumor suppressor by targeting KRAS in NSCLC." (PMID 31871778, 2019). "The observation of a prognostic interaction of PR expression and KRAS mutation status is however noteworthy, as it suggests that PR-mediated signaling may have tumor suppressing effects in KRAS-mutated tumors and tumor-promoting effects in KRAS wild-type tumors." (PMID 31827798, 2019). "Indeed, concordance studies have been carried out between the presence of the KRAS mutation in the primary tumour and the search for the mutation in ctDNA: the concordance varies from 25% to 75% and finally the sensitivity of this approach is highly dependent on the nature of the tumour." (PMID 31248203, 2019). "Therefore, we hypothesize that minor tumor clones carrying KRAS variants might be enriched during tumor progression in the metastatic sites, thus determining resistance to anti-EGFR MoAbs and positivity of liquid biopsy." (PMID 31226844, 2019).
tumor (continued). "Overall, the KRAS mutation of the tumor could be observed in the juice DNA in 18 cases (86%)." (PMID 30611220, 2019). "The absence of the BRAF mutation in the juice of case #10 suggests that the fluid contained little DNA arising from the tumor, and that the KRAS mutation may have its origin somewhere else, most likely in the tail region of the pancreas drained by the distal duct." (PMID 30611220, 2019). "Therefore, we hypothesized that more tumor-associated KRAS mutations related to drug-resistant or tumor recurrence and metastasis may be detected in those CSCs." (PMID 29755662, 2018). "Secondly, our KRAS mutation analysis used the tumor genetic codes obtained from NGS sequencing, with an average sequencing depth around 100×, which may yield false negative mutation callings or mosaiced mutational allele estimation in cancer types with extremely low tumor cellularity." (PMID 30406144, 2018). "The identification of convergence between KRAS signaling and NURD/MYC epigenetic reprogramming may inform evidence-based clinical trial development for metastatic lung cancer patients with activated KRAS mutations, or even potentially other tumor types with KRAS mutations." (PMID 30013058, 2018). "First, an acquired KRAS mutation in the tumor may travel to the blood." (PMID 29849949, 2018). "Some studies reported that the concordance in KRAS mutational status between the primary and the metastatic tumours is high, and tissue from either the primary tumour or metastasis may be used for testing mutations according to the latest NCCN guidelines for the treatment of mCRC." (PMID 30171333, 2018). "KRAS mutation subtypes might induce different tumor biology in the same tumor type." (PMID 30419860, 2018). "In our sample, 2 of 6 patients with a KRAS mutation (33%) had some degree of heterogeneity found in the sample; therefore, a recommendation can be made that that at least two biopsies from different parts of the tumour be taken to take the heterogeneity into consideration." (PMID 28097409, 2017). "Thus, we assumed that patients with advanced NSCLC harboring KRAS mutations might show better outcomes to ICIs than those with KRAS wild-type tumor." (PMID 28525386, 2017). "In genetic polymorphisms analysis, we found that the KRAS rs1137188 variant AA genotype had higher portion of tumor size (≥ 5 cm) (P = 0.01; Bonferroni-adjusted P = 0.04), which suggested that the rs1137188 variant AA genotype may significantly be associated with increased progression of CRC." (PMID 28328959, 2017). "However, 46 (30.3%) oncologists indicated that their patients were tested for KRAS tumour mutation status only, and the remaining 58 (38.2%) indicated that while some patients were tested for RAS tumour mutation status, some patients had only been tested for KRAS tumour mutation status." (PMID 29183279, 2017). "Since tumor-specific KRAS mutations were detected in only 58.5% of plasma samples from metastatic CRC patients whose tumors had known KRAS mutations, we investigated whether this low detection rate was due to technical limitations of our methods or due to low abundance of tumor DNA in plasma." (PMID 28459822, 2017). "Especially in second line therapy of CRC, with median times to progression of a only a few months, it is unlikely a single cell acquiring a KRAS mutation or even a pre-existing clone could become a substantive portion of a tumor that even at 2 cm in diameter has approximately 8 billion cells." (PMID 28981524, 2017). "In addition, objective responses have been detected in patients with KRAS-mutated tumours." (PMID 28032593, 2017). "In that study, two cases with different morphological features exhibited the same KRAS mutation (similar to our case 5) while one case with morphologically similar tumours had discordant KRAS mutation status suggesting separate synchronous primary tumours (like our case 4)." (PMID 28347348, 2017).
tumor (continued). "This KRAS status could be due to intratumoral heterogeneity—i.e., the few cells harboring this mutation may have been overshadowed by wild-type cells, which constituted the majority of the tumor cells." (PMID 28830562, 2017). "In this study, the presence of KRAS mutations was also significantly associated with the tumour being sited at the body, tail or neck of the pancreas (p=0.015), known to have an inferior survival outcome compared to the tumour being sited in the head of the pancreas." (PMID 29152076, 2017). "However, due to intratumoral heterogeneity KRAS mutation heterogeneity within different areas of the tumor might be a potential concern as recently reported at least for selected patients." (PMID 27064574, 2016). "However, there was a tendency towards a higher ORR (87.5% vs 55.6%), longer PFS (median 12.0 vs 7.0 months), and longer OS (median 30.0 vs 7.0 months) among patients whose tumours were KRAS exon 2 wild type compared with those whose tumours harboured KRAS exon 2 mutations." (PMID 26766738, 2016). "Similarly, retrospective data suggest that patients whose tumours harbour the specific KRAS G13D mutation may be sensitive to EGFR-I, in contrast to all other KRAS mutations." (PMID 27246726, 2016). "Moreover, KRAS mutations were found to be rare and all tumours were EGFR wild-type." (PMID 26844548, 2016). "Genomic DNA from primary tumour tissues of 1284 consecutively-collected patients with metastatic colorectal carcinoma (mCRC), originating from different geographical areas within Sardinia island, was screened for somatic mutations in KRAS, NRAS, BRAF, and PIK3CA genes." (PMID 27737711, 2016). "Importantly, these feedbacks and cross-talk can shape the response of tumor cells to targeted therapies, which may be different depending on mutations in the pathway, such as in KRAS or BRAF genes." (PMID 26799289, 2016). "Although further investigation of the correlation between expression in cancer cells and in the interstitium is required, our results suggested that RCAN2 is predominantly expressed at the IF and that KRAS-mutated CRC may promote tumor development due to decreased expression of RCAN2." (PMID 27526107, 2016). "Mutation in KRAS gene occurs early in the development of cancer and may therefore play an important role in several stages of cancer progression and development of malignancy including the initiation of neoplasia and metastasis and prediction of prognosis." (PMID 25685149, 2015). "Interestingly, one tumor displayed both KRAS codon 12 and 13 mutations." (PMID 26207151, 2015). "Reports of improved efficacy with panitumumab and cetuximab in patients with wild-type versus mutant or unknown KRAS exon 2 status led to the requirement for physicians to determine a patient’s tumor KRAS mutation status prior to starting treatment with EGFR inhibitors." (PMID 26491871, 2015). "By applying the same ‘exclusivity analysis’ to mutation data from other tumor types, however, we identified or confirmed other pairs of mutations—mutant KRAS and BRAF in COAD, mutant EGFR and NF1 in GBM, and mutant BRAF and NRAS in SKCM —that may be synthetically lethal in those tumors." (PMID 26047463, 2015). "Similarly, KRAS hotspot mutations were identified in five cases and tumours of these patients may respond to MEK/BRAF inhibitors." (PMID 25233892, 2014). "These conflicting reports were then reconciled by a large retrospective consortium analysis on 1,022 tumor samples which showed that, in the KRAS wild-type subpopulation, only PIK3CA exon 20 mutations may be predictive of lack response to cetuximab (RR of 0 % in mutant vs 36.8 % in wild-type cases)." (PMID 24811491, 2014). "However, a recent review of 11 clinical studies, reported that 29%-100% of patients presented with the same KRAS mutation in both blood and tumor samples suggesting that blood samples may also be suitable for determining KRAS status." (PMID 25491325, 2014).
tumor (continued). "A total of 529 patients from the CAIRO2 study were included in this analysis, 266 patients were excluded based on unknown KRAS mutation status, due to retrospective genotyping of the KRAS mutation status of the tumor, because the CAIRO2 study was performed in the pre KRAS era." (PMID 25375154, 2014). "By this assay, KRAS mutations could be consistently identified from 10 spiked tumor cells." (PMID 25137394, 2014). "We postulated that, in addition to KRAS-mutated DNA fragments, other tumor DNA fragments should be present in the circulation of these patients and that these might provide insights about the tumor genome." (PMID 23319339, 2013). "Interestingly, loss of tumor supressor LKB1 coexists with KRAS oncogenic mutations and synergizes in tumor formation and progression, however, its cooperation with BRAFV600E oncogene is unknown." (PMID 23825589, 2013). "KRAS mutation status could be assessed in 153/154 (99.3%) tumours." (PMID 23800114, 2013). "Interestingly, we observed tumor shrinkage in one patient with a KRAS mutation." (PMID 24039832, 2013). "However, the fact that even a pure sample of tumor cells may contain large quantities of wild-type KRAS further complicates the selective identification of mutations in this gene." (PMID 22995035, 2012). "However, in our selected good responders, 6 patients (35%) had a KRAS mutated tumour." (PMID 22804917, 2012). "Furthermore, whether KRAS mutations are stable or whether they undergo clonal evolution during tumour progression remains a matter of debate." (PMID 23226727, 2012). "Therefore, KRAS mutations are predicted to be identical in primary tumour and metastatic tissues." (PMID 23226727, 2012). "Therefore, it is still uncertain whether the evaluation of KRAS mutation status in the most commonly available primary tumour correctly reflects the KRAS mutation status of corresponding metastasis." (PMID 21364579, 2011). "Therefore, KRAS mutation status is expected to be equal in both primary tumours and metastases." (PMID 21364579, 2011). "In addition, this unfavourable effect of TOPK expression on outcome was maintained in multivariate analysis, suggesting that TOPK could represent an important prognostic factor in patients with KRAS-mutated or BRAF-mutated tumours." (PMID 19935791, 2010). "Therefore, KRAS mutation detection with SNaPshot could have a more enhanced role in response prediction of therapy depending on which response can be expected due to the amount of mutated KRAS allele in the tumor." (PMID 21197450, 2010). "KRAS mutations were detected in many samples with a very low tumor cell count, and the frequency of KRAS codon 12 or 13 mutations in tissues with a low (< 10%) tumor cell content (36% mutation rate) was similar to that of tissues with ≥10% tumor cells (37% mutation rate)." (PMID 21122130, 2010). "However, when more potent agents of this type are developed, they will need to be determined whether their efficacy is influenced by the presence of KRAS mutations in the tumor." (PMID 19386128, 2009). "This may reflect a more indolent course of tumours with KRAS/BRAF mutations." (PMID 19018267, 2008). "In non-KRASG12D-mutant models, MRTX1133 + cetuximab modestly reduced KRAS pathway activity and slightly delayed tumor growth, consistent with a potential 'leakage effect'." (PMID 42209458, 2026). "Recent studies suggest that mutations in KRAS drive mevalonate pathway activation, enhancing YAP/TAZ signaling and amplifying tumor-initiating properties." (PMID 41550359, 2026). "Robin's team conducted clinical trials to evaluate the efficacy of MEK inhibitors in the downstream signaling pathway of KRAS in combination with pan-HER-2 inhibitors in KRASG12C-mutant tumor groups." (PMID 41362725, 2026). "We focus specifically on KRAS-driven cancers, where persistent oncogenic signaling enhances SG formation and stability, making these condensates critical mediators of tumor adaptation." (PMID 41772378, 2026).